ACE (angiotensin I converting enzyme)
Diseases named in the same sentence as ACE in open-access papers (continued):
Sharing a sentence is not in itself a finding about the gene and the disease.
COVID-19 (continued). "The objective of this review is to describe the anti-hypertensive activity present in some bioactive compounds in cereals, wherein activities such as the inhibition of ACE, its participation in oxidative stress, and its consumption could be associated with the prevention of COVID-19." (PMID 37430980, 2022). "In addition, COVID-19 is associated with an increased risk of post-acute sequelae involving renal systems, where ACE axis elements are expressed, and most circulating RAS proteins are filtered by the renal glomeruli before being reabsorbed by the proximal tubule." (PMID 35566253, 2022). "However, the clinical implication of ACE genetic variants in the severity and prognosis of COVID-19 remains unclear." (PMID 35250987, 2022). "In addition, prospective analysis regarding the impact of ACE/ACE2 polymorphisms or SNP analysis affecting the clinical outcome of COVID-19 patients might lighten the impact of RAAS in the context of COVID-19." (PMID 35685188, 2022). "There is increasing interest in intestinal infection as a route of viral spread; among people taking ACE inhibitors, associated increases in small intestine ACE2 could potentially increase the risk of SARS-CoV-2 viral infection." (PMID 35359831, 2022). "Moreover, an imbalance in tissue ACE/ACE2 activity is implicated in COVID-19." (PMID 34359878, 2021). "The viral structural spike (S) protein binds to the angiotensin-converting enzyme 2 (ACE2) receptor to gain entry to cells; this has led to suggestions that use of ACE inhibitors and angiotensin II type-I receptor blockers (ARBs) may be implicated in poorer outcomes with COVID-19." (PMID 33483621, 2021). "Thus, a lot of individuals taking ACE inhibitors may have an increased risk of urticaria/angioedema after COVID-19 vaccination." (PMID 34579248, 2021). "Indeed, an Alu variant within the ACE gene has already been hypothesized to impact COVID-19 susceptibility and morbidity and, in light of this, several Alu variants are likely influencing host response pathways." (PMID 33390179, 2021). "Moreover, the use of drugs that increase NO availability (e.g., ACE inhibitors) has been associated with favorable COVID-19 outcomes, whereas treatment with drugs inhibiting NO production/release (e.g., proton pump inhibitors) has been associated with worse COVID-19 prognosis." (PMID 34830738, 2021). "Furthermore, ACE polymorphism might represent a genetic risk factor to thromboembolism in COVID-19 patients." (PMID 34834033, 2021). "In addition, prebiotics may have a direct effect on GI symptoms caused by COVID-19 by blocking ACE enzymes, and ACE2 is thought to be a gateway for SARS-CoV-2 to bind and attack the body." (PMID 35004750, 2021). "Finally, the role of ACEI/ARBs in COVID-19 disease is still unresolved and it would be interesting to evaluate whether there is any interaction between ACE polymorphisms and these drugs in the SARS-COV2 setting." (PMID 35004773, 2021). "However, this particular phenomenon might be of potential advantage in dosing and management of severity of COVID-19-associated morbidities in African American and other ethnic populations with ACE deletion polymorphism." (PMID 32901433, 2021). "It has been hypothesized that patients taking ACE inhibitors or ARBs might be at increased risk for more severe COVID-19 based on SARS-CoV-2 binding to ACE2 receptors found on epithelial cells in the respiratory tract as well as in intestine, kidney, and blood vessels." (PMID 34473791, 2021). "Other reports hypothesized that ACE inhibitors and nicotine exposure may be associated with cardiorespiratory manifestations in COVID-19 due to upregulation of ACE-2 receptors (which is essential for SARS-COV-2 cell entry), however this remains to be properly studied." (PMID 34006330, 2021).
COVID-19 (continued). "Notably, lung function is impaired in comorbidities linked to increased risk of severe COVID-19 including obesity and type 2 diabetes; furthermore, most cardio-metabolic comorbidities have been linked to increased expression of the angiotensin converting enzyme (ACE)." (PMID 33326502, 2020). "Moreover, different ACE polymorphisms were observed in different races, and this may suggest a possible link with the COVID-19 diffusion and with the different outcome observed throughout the world." (PMID 32867137, 2020). "It is still controversial as to whether patients receiving ACE inhibitors or angiotensin-receptor blockers could show enhanced susceptibility to SARS-CoV-2 infection or COVID-19 severity through increased ACE2 expression or attenuated inflammation and fibrosis, respectively." (PMID 33374416, 2020). "Our result suggesting that the combination of rs4646994 of the ACE gene and rs75603675 of the TMPRSS2 gene is associated with increased risk of severe COVID-19." (PMID 41734172, 2026). "In terms of combined genetic effects, polymorphisms in ACE, ACTN3, and PPARGC1A likely interact to influence COVID-19 outcomes." (PMID 40150043, 2025). "Based on this background, the present study is set to investigate the roles of the ACE rs4646994, ACTN3 rs1815739, and PPARGC1A rs8192678 polymorphisms in determining the severity of COVID-19 outcomes." (PMID 40150043, 2025). "Concerns were raised about the use of RAAS inhibitors (RAASi), such as ACE inhibitors (ACEi) and angiotensin receptor blockers (ARBs), in COVID-19 patients, due to the potential upregulation of ACE2." (PMID 40217682, 2025). "The results showed that rutin exhibited a strong inhibitory effect on FXR/RXR, DPP4, JAK2, and ACE, suggesting its potential as a therapeutic agent for modulating these COVID-19-related targets." (PMID 40076279, 2025). "Among the 19 intersecting targets identified between G. pentaphyllum compounds and COVID-19-associated genes, several key nodes—IL1B, IL6, TNF, ACE, and REN—emerged as central in both the protein–protein interaction and compound–target networks." (PMID 41471341, 2025). "Pharmacological therapies that improve endothelial function, such as antioxidants, statins, ACE inhibitors/ARBs, and metformin, have shown promise in addressing long-term vascular dysfunction induced by COVID-19." (PMID 39766328, 2024). "The phenotypic data complement this observation with the elevated use of ACE inhibitors in severe COVID-19 cases." (PMID 38750426, 2024). "Numerous studies have found a link between the usage of ACE inhibitors and a decreased incidence of COVID-19, despite some controversy." (PMID 38633607, 2024). "Of note, serum ACE level was constantly increased across the severity of COVID-19 as severe and critical cases had markedly elevated ACE serum levels compared to those with moderate and mild clinical types." (PMID 38177248, 2024). "Lentils possess angiotensin I-converting enzyme (ACE) inhibitory properties, and the beneficial impact of ACE inhibition on COVID-19 requires further investigation and consideration." (PMID 38501131, 2024). "Furthermore, data show that COVID-19 susceptibility may be associated with ACE I/D polymorphisms." (PMID 39194697, 2024). "This discussion has become even more evident with the emergence of COVID-19, since the novel coronavirus SARS-CoV-2 causes ACE/ACE2 balance disruption by using ACE2 as a receptor to enter host cells." (PMID 39273464, 2024). "In conclusion, the imbalance of RAS in COVID-19 leads to cellular fibrosis through virus-mediated downregulation of ACE2 in favor of the pro-fibrotic ACE/Ang II/AT1R axis." (PMID 39444690, 2024). "Genetic polymorphisms in ACE and ACE2 have been implicated in disease progression, prompting our investigation into their role in COVID-19 evolution." (PMID 39194697, 2024). "SARS-CoV-2 causes ACE/ACE2 balance disruption and RAAS activation, which ultimately leads to COVID-19 progression." (PMID 39591276, 2024).
COVID-19 (continued). "In this study, we investigated the impact of the ACE gene insertion/deletion (I/D) polymorphism and PTX3 levels on the severity of radiographic pulmonary infiltrates and the clinical outcomes of COVID-19." (PMID 39062191, 2024). "Among n=32 (7%) COVID-19 patients who were already on ACE or angiotensin receptor blocker (ARB), only four (8.9%) developed AKI (p=0.54)." (PMID 38715992, 2024). "In an attempt to explain our findings, we have investigated ACE serum level in patients with COVID-19 which was significantly higher compared to the control group." (PMID 38177248, 2024). "Four of these genes (ACE, KLF5, IDO1, and CDC25A) have been reported to be associated with the pathological mechanisms of COVID-19 and sarcopenia." (PMID 38978778, 2024). "This article will discuss several issues related to the use of generic drugs (including but not limited to statins, ACE inhibitors (ACEis), and angiotensin receptor blockers (ARBs)) to treat patients with COVID-19." (PMID 36983871, 2023). "Some anti-hypertensive medications like ACE inhibitors/ARBs impact COVID-19 further than controlling high blood pressure, which goes back to the infection mechanisms relying on the renin–angiotensin system (RAS)." (PMID 38164450, 2023). "The wide variances in COVID-19 death rates might be explained by significant alterations in the equilibrium of the ACE:ACE-2 system associated with gender, racial, and age differences in genetic ACE and ACE-2 polymorphism and environmental aspects manipulating ACE-2 expression." (PMID 37240292, 2023). "Sub-acute exposure to PM2.5 causes alterations in the ACE/ACE2 system, with possible consequences on COVID-19 pathogenesis." (PMID 36901403, 2023). "Using BK degradation for measuring the protease (CPN and ACE) activity in patients’ sera, we noted a general reduction in the BK degradation capacity in hospitalized COVID-19 patients, but also in some convalescent patients." (PMID 37511837, 2023). "Genotypic frequency distribution for the combination of ACE I/D and ACE2 G8790A polymorphisms in moderate and severe COVID-19 groups and risk analysis for the outcome in COVID-19." (PMID 38032879, 2023). "As binding between glycoprotein S and ACE2 is such a crucial step in COVID-19 pathogenesis, several studies analyzed the connection between the use of ACE inhibitor drugs and SARS-CoV-2 infection." (PMID 37189632, 2023). "Because ACE2 was inhibited by MHV-1 and/or PD-L1mAb in our model, angiotensin substrates favor ACE cleavage and downstream proinflammatory responses, as occurs in COVID-19." (PMID 38259435, 2023). "Another study showed an increased ACE activity in fatally ill patients with COVID-19, which indicated dysregulation of the RAAS in the infection." (PMID 37432962, 2023). "ACE levels were higher in patients who died during COVID-19 (29.6 ng/mL vs 17.4 ng/mL, p = 0.023) and were admitted to the ICU (37.2 ng/mL vs 16.7 ng/mL, p<0.001)." (PMID 37432962, 2023). "Nevertheless, GG genotype and G allele carriers, associated with lower serum ACE levels, were shown to have an increased risk of SARS-CoV-2 infection and a more severe course of COVID-19." (PMID 36835445, 2023). "Another systematic review and meta-analysis revealed that genetic variants within the angiotensin-converting enzyme 1 and 2 genes (ACE and ACE2, respectively) and the transmembrane serine protease 2 (TMPRSS2) gene were associated with COVID-19 severity." (PMID 38113267, 2023). "A key molecular connection between the severity of COVID-19 and insulin resistance is likely the angiotensin-converting enzyme (ACE), which is abundantly found in pancreatic beta cells." (PMID 38192935, 2023). "Logistic regression analysis was applied to analyze the association between ACE-2 and IFITM-3 genetic variants, IL-6 profile, and COVID-19 severity." (PMID 38155729, 2023).
COVID-19 (continued). "Apart from anti-A antibodies, the link between group A and severe COVID-19 is increased activity of angiotensin-converting enzyme 1 (ACE-1), with a tendency for cardiovascular complications." (PMID 37151755, 2023). "Previous data showed a higher prevalence of ACE D/D genotype in severe COVID-19 patients as compared to those with less severe disease." (PMID 36371754, 2023). "In this sense, lower serum ACE activity can be observed in patients with severe COVID-19, and activity levels are restored when patients are recovered (post-COVID-19 group)." (PMID 37108839, 2023). "Several studies have investigated the role of ACE and ACE2 gene polymorphisms in COVID-19 susceptibility and disease severity." (PMID 37667339, 2023). "Considering COVID-19 together with chronic diseases and their treatments, ACE levels were similar between the patients with T2DM treated with or without DPP-4i." (PMID 37432962, 2023). "It is worth noting that increased concentration of ACE, and dysregulation in ACE/ACE2 balance, has been observed in diseases associated with ARDS, like in patients with severe COVID-19." (PMID 36411399, 2023). "Previous data showed a higher prevalence of ACE D/D genotype in severe COVID-19 patients compared to those with mild disease; this genotype is significantly associated with cardiometabolic diseases and obesity, known risk factors for COVID-19." (PMID 37240292, 2023). "Further analyses are needed to elucidate the enigmatic role of the enzymes ACE2 and ACE as well as renin in the RAS system in the context of COVID-19." (PMID 36851710, 2023). "A prospective, multicentric study, led by the group of Hakeam, enrolled a group of 338 patients who had been recovering in hospital because of COVID-19, all of them under ACE inhibitor prescriptions, with only 197 continuing therapies during hospitalization." (PMID 37189632, 2023). "Genotypic frequency distribution of ACE I/D and ACE2 G8790A polymorphisms in the moderate and severe COVID-19 groups and risk analysis for the outcome in COVID-19." (PMID 38032879, 2023). "The current study sought to assess the impact of ACE and ACE2 polymorphisms on the prognosis of COVID-19 patients with a confirmed diagnosis of SARS-CoV-2 infection being treated in a field hospital in Goiânia, GO, Brazil." (PMID 38032879, 2023). "Further studies involving larger sample size and more diverse populations should be conducted to provide better understanding of the relationship between the ACE-1, ACE-2 and TMPRSS2 polymorphism and COVID-19 disease severity." (PMID 37426824, 2023). "There have been consistent data suggesting that COVID-19 is associated with more severe symptoms and disease course in subjects with COPD in relation to the role played by angiotensin converting enzyme 2 (ACE)." (PMID 37631960, 2023). "It seems to act as a protective means to attenuate systemic classical ACE/Ang II/AT1R proinflammatory pathway in COVID-19." (PMID 36851081, 2023). "This study highlights the relevance of ACE and serum ACE activity in COVID-19 and other respiratory diseases." (PMID 37108839, 2023). "Post-COVID-19 exhibited lower levels of serum IL-6 (p adj <0.01), whereas it showed higher serum IL-10, triglyceride, leptin, IgG, ACE activity, TNFRSF1A, and PGE2 (p adj <0.05) levels compared with controls." (PMID 37753077, 2023). "Hardy-Weinberg equilibrium test for ACE I/D and ACE2 G8790A polymorphisms in moderate and severe groups of COVID-19." (PMID 38032879, 2023). "Individuals with a D/D genotype, which leads to an increased serum ACE concentration, were shown to have higher rates of pulmonary embolism and COVID-19-related mortality." (PMID 36835445, 2023). "Variables in the multifactorial logistic regression analysis for ACE I/D and ACE2 G8790A polymorphisms in the moderate and severe COVID-19 groups." (PMID 38032879, 2023).
COVID-19 (continued). "This study also showed that comorbid hyperlipidemia and a history of SGLT2 inhibitor, ACE inhibitor, ARB, glucocorticoid, and statin use were associated with a decreased risk of COVID-19 severity." (PMID 37542210, 2023). "The present prospective cohort study aims to assess the association between the ACE-1 rs4343, ACE-2 rs908004 and TMPRSS2 rs12329760 genes and the COVID-19 clinical severity in Egyptian patients." (PMID 37426824, 2023). "One of the molecular factors involved in COVID-19-related AF episodes is the angiotensin-converting enzyme (ACE) 2 availability." (PMID 36755799, 2023). "Most studies agree that a higher link exists between the ACE deletion/deletion (D/D) genotype and severe COVID-19." (PMID 37175942, 2023). "Moving on to the predictive medications as extracted from the medication administration and order records, the use of HMG CoA reductase inhibitors and ACE inhibitors exhibited the highest predictive importance among pre-COVID-19 medications." (PMID 38068365, 2023). "Post-COVID-19 serum of elderly patients had a significantly decreased capacity to block the fusion of SARS-CoV-2 spike with ACE-expressing cells, as revealed by studying high dilutions of the patient serum." (PMID 36010162, 2022). "Because of the upregulation of ACE2 through ACE-inhibitors, an adverse effect of ACE-Inhibitors in COVID-19 has been controversially discussed." (PMID 35548445, 2022). "Extreme thirst, an uncommon symptom of COVID-19 patients, is often seen with elevated BK and ACE inhibitor levels." (PMID 35153624, 2022). "The effect of genetic polymorphisms on immunity after COVID-19 has been well-reported in limited types of genes encoding proteins directly related to the immune response to SARS-CoV-2, such as ACE and HLA." (PMID 35891198, 2022). "An analysis of COVID-19 clinical outcomes among people taking ACE inhibitor or ARB monotherapy vs. combination therapy could provide valuable observational data on the potential benefits of combination therapy in reducing susceptibility or severity of COVID-19." (PMID 35359831, 2022). "Therefore, it is suitable to study the effect of ACE inhibitors and angiotensin II type I-receptor blockers that are used to treat diabetics and can result in upregulation of hACE-2, thereby potentially sensitizing patients for severe SARS-CoV-2 infection." (PMID 35798721, 2022). "Specifically, in severe COVID-19, we observed a reduced angiotensin II:I ratio, used as a marker for functional ACE activity, a reduction that was partially explained by an overall shift to the alternative RAS axis because of increased ACE2 levels." (PMID 36418458, 2022). "Due to the fact that it is the cell receptor to which the viral spike protein binds, ACE has been investigated as a potential target for COVID-19 therapy." (PMID 35163923, 2022). "Besides, several studies have strongly suggested that some ACE polymorphisms could induce susceptibility to COVID-19, whereas others are resistant to this disease due to their low binding ability with SARS-CoV-2 glycoprotein S, as demonstrated by affinity experiments." (PMID 35062298, 2022). "Our study demonstrated the correlation of the activity of the serum proteases CPN and ACE with disease severity in COVID-19." (PMID 35330406, 2022). "There is another aspect of interest related to the use of ACE inhibitors or ATR blockers in COVID-19 patients." (PMID 35163923, 2022). "The COVID-19 virus enters the brain via angiotensin-converting enzyme (ACE)-2 receptors present in the CNS and is particularly expressed in the nasal mucosa." (PMID 35883527, 2022). "In the present study, we focused on the angiotensin-converting enzyme (ACE) Del/Del genotype that was once reported to be associated with progression of the severe acute respiratory syndrome (SARS) and COVID-19." (PMID 35571459, 2022).